RPS27 (ribosomal protein S27)
Diseases named in the same sentence as RPS27 in open-access papers:
RPS27 is named in the same sentence as 33 diseases in open-access papers, as found by Europe PMC text mining. Sharing a sentence is not in itself a finding about the gene and the disease. The quoted sentences say what the papers report.
gastric cancer (9 papers, 2017 to 2025). A primary or metastatic malignant neoplasm involving the stomach. "Previous studies have demonstrated the upregulation of RPS27 expression in various human malignancies, such as melanoma and gastric cancer." (PMID 40280903, 2025). "Elevated RPS27 levels have previously been observed in various cancer types, including breast cancer, gastric cancer, colorectal cancer, and liver cancer, and are associated with a poorer prognosis." (PMID 38365771, 2024). "Ribosomal protein S27 (MPS-1) is highly expressed in gastric cancer cells and is related to the metastasis of gastric cancer cells." (PMID 34439865, 2021). "Recent studies have shown that RPS27/MPS-1 is overexpressed in 86% of gastric cancer tissues, and its overexpression is related to tumor nodule metastasis." (PMID 31921103, 2019). "In gastric cancer cells, the expression of RPS27/MPS-1 affects the NF-κB pathway of gastric cancer cells." (PMID 31921103, 2019). "Interestingly, RPS27 has been found to be highly expressed in gastric cancer tissue and cancer cells, correlating with the expression of integrin ß4 that has been demonstrates to promote invasion and migration in various tumours." (PMID 36226068, 2022). "Many RPs are found affected in gastric cancer (GC) including RPS13, RPL23, RPS27, RPL6, RPL13 and RPL15." (PMID 34873618, 2021).
melanoma (8 papers, 2014 to 2025). A malignant, usually aggressive tumor composed of atypical, neoplastic melanocytes. "RPS27 mutation and its elevated expression have been detected in many melanoma patients and in various human cancers." (PMID 31001324, 2019). "Our comparative analysis of several next generation sequencing studies retrieved a novel recurrent mutation located at the TSS of the RPS27 gene in ~10% of the melanoma cases." (PMID 24913145, 2014). "Mutations in the RPS27 promoter may be a mechanism of gene expression regulation in patients with melanoma, which may have prognostic and predictive significance." (PMID 34355024, 2021). "Subsequent in vitro functional studies showed that the RPS27 5’UTR hotspot mutation decreases RPS27 mRNA levels and that decreased levels of RPS27 are associated with a worse prognosis of melanoma patients and drug (vemurafenib and palbociclib) sensitivity of melanoma cells." (PMID 34900699, 2021). "RPS27 positivity has been observed for macrophages associated with melanomas." (PMID 32349320, 2020). "The two newly discovered regulatory mutation blocks may contribute to the dysregulation of RALY and RPS27 and are worthy for further investigation because both genes are known to be significantly associated with melanoma." (PMID 31001324, 2019). "Also, low expression of RPS27 is associated with poor clinical prognosis in melanoma." (PMID 33305312, 2021). "Mutations in the promoter/5’UTR of RPS27 (including the hotspot mutation) have been identified before in ~10% of melanoma samples but have never been reported in BCC or other skin cancers." (PMID 34900699, 2021). "For melanoma, it has been discussed that cells with high RPS27 expression were characterized by higher proliferation and invasion capabilities, whereas RPS27 low cells displayed a reduced adherence, higher anchorage-independent survival, and more aggressive and drug-resistant behavior." (PMID 32349320, 2020). "Interestingly, it was previously reported that the mutation from a C to a U at Chr1: 153963239, the TSS of RPS27, causes the 5′ TOP motif to expand (5′-CUUUUCCG) and is associated with a higher frequency of melanomas." (PMID 28977652, 2017). "The RPS27 gene is overexpressed in several malignancies, including melanoma." (PMID 24913145, 2014).
breast carcinoma (5 papers, 2004 to 2024). "Cluster 1 and cluster 2 had no specific enriched breast cancer signatures however cluster 1 had several ribosomal and ER stress-associated genes (Rpl41, Rps27, Rps29, Fosb, and Jund)." (PMID 35851387, 2022). "Contradicting our results, previous studies have shown that low expression levels of ribosomal proteins RPS9, RPS14, RPS27, RPL11 and RPL14 are related to a poor overall survival in breast cancer patients, especially in TNBC." (PMID 37888706, 2023).
colorectal cancer (3 papers, 2017 to 2025). A primary or metastatic malignant neoplasm that affects the colon or rectum. "Evidence suggests that HSPA4, HSP90AB1, DNTM1, RPS27, FTL, NCL, A2M are implicated in the pathogenesis and progression of colorectal cancer, positioning them as potential prognostic biomarkers for the onset of metastasis." (PMID 41319168, 2025). "In colorectal cancers, RPS27 promotes cell proliferation by activating the JNK/c-Jun signaling pathway." (PMID 38365771, 2024).
glioma (3 papers, 2022 to 2023). A benign or malignant brain and spinal cord tumor that arises from glial cells (astrocytes, oligodendrocytes, ependymal cells). "RPS27 is overexpressed in GB and gliomas of grade II/III, glioma stem-like cells, and macrophages associated with the tumor tissue." (PMID 36994107, 2023). "RPS27 is overexpressed in many tumors, but its role in CNS tumors such as gliomas wasn’t elucidated until recently." (PMID 36425564, 2022). "As for brain tumors, in a previous study, the mRNA of RPS27 was 6.2- and 8.8-fold (mean) enhanced in gliomas of WHO grades II and III with (p < 0.01) and without IDH mutation (p = 0.01), respectively, compared with that in the normal healthy brain." (PMID 35883585, 2022). "However, the expression of RPS27 was not related to the WHO grade in gliomas." (PMID 35883585, 2022).
astrocytic tumor (2 papers, 2020 to 2022). A glial tumor of the brain or spinal cord showing astrocytic differentiation. "In summary, we found RPS27 overexpressed in astrocytic tumors, independently of their WHO grade, IDH-mutation status, or tumor/patient characteristics." (PMID 32349320, 2020). "We stained glioma WHO grade II/III and GBM tissue from patients, both revealing clear RPS27 expression by astrocytic tumor cells." (PMID 32349320, 2020). "Thus, we aimed to identify RPS27 expressing cells in the CNS with special emphasis on astrocytic tumors." (PMID 32349320, 2020). "In contrast, looking at GBM tissue, double staining of RPS27 with GFAP was obvious, indicating the astrocytic tumor cells." (PMID 32349320, 2020). "Analysis of healthy, inflamed, neurodegenerative, and cancer brain tissues using IHC, and mRNA sequencing revealed that RPS27 was expressed in all neurons examined and in astrocytic tumor cells but not in normal astrocytes." (PMID 36425564, 2022). "Interestingly, RPS27 was not detectable in normal astrocytes, but clearly present in astrocytic tumor cells." (PMID 32349320, 2020).
Diamond-Blackfan anaemia (2 papers, 2022 to 2024). "Also, for the Blanco Orejinegro and Limonero, RPS27 and RPS20 are located in CSS cluster regions on BTA3 and BTA14, respectively, and mutations in these genes can cause Diamond-Blackfan anaemia." (PMID 38571912, 2024).
Alzheimer disease (1 paper, 2020). A progressive, neurodegenerative disease characterized by loss of function and death of nerve cells in several areas of the brain leading to loss of cognitive function such as memory and language. "Specimens of the neurodegenerative Alzheimer’s disease confirmed the data on RPS27 expression by Purkinje cells, neurons, and its absence in astrocytes." (PMID 32349320, 2020).
colon cancer (1 paper, 2021). "On the other hand, RPS27 KD is linked to inhibition of colon tumor progression by impeding the JNK/c-Jun signaling pathway and promoting leptin circulation, especially in obese CRC patients in vivo." (PMID 34873618, 2021). "Similarly, the knockdown of RPS9, RPS15a and RPS27 inhibit human colon cancer cell growth and proliferation." (PMID 34873618, 2021). "Interestingly, RPS27A, a family member of RPS27 similar to c-jun and c-fos, is shown to be also overexpressed in human colonic cancer." (PMID 34873618, 2021).
glioblastoma (1 paper, 2023). The most malignant astrocytic tumor (WHO grade IV). "For example, with glioblastoma, eS6 (RPS6), eS27 (RPS27), uS8 (RPS15A) and eL34 (RPL34) are known as oncogenic, whereas uL18 (RPL5), uS17 (RPS11), uS9 (RPS16) and uS13 (RPS18) are found to have a tumor-suppressive function." (PMID 37511213, 2023).
leukemia (1 paper, 2021). A malignant (clonal) hematologic disorder, involving hematopoietic stem cells and characterized by the presence of primitive or atypical myeloid or lymphoid cells in the bone marrow and the blood. "The expression of RPS27, which was highly expressed in ccRCC tissues compared with controls, promoted proliferation and inhibited the apoptosis of leukemia cells." (PMID 33959493, 2021).
lung fibrosis (1 paper, 2020). "ZnO specific gene signature further englobed the overexpression of Pla2g16 (FC + 7) a membrane damage sensor; S100a4 (FC + 7) involved in macrophage-induced lung fibrosis; Rps14 (FC + 6), Rps27 (FC + 5), and Mrps15 (FC + 5), three protein synthesis regulators." (PMID 31352547, 2020).
oligodendroglial tumor (1 paper, 2020). Oligodendrogliomas are cerebral tumors that are differentiated from other gliomas on the basis of their unique genetic characteristics and better response to chemotherapy. "We observed a significantly enhanced copy number of the RPS27 gene in oligodendroglial tumors WHO grade III by the Oncomine analysis tool based on the ‘The Cancer Genome Atlas’ (TCGA) brain 2 dataset (p < 0.01)." (PMID 32349320, 2020).
prostate adenocarcinoma (1 paper, 2024). "RPS27 was also found to be positively correlated with these genes in prostate adenocarcinoma patients." (PMID 38365771, 2024).
prostate tumor (1 paper, 2024). "RPS27 expression levels were assessed in various prostate tumor cell lines." (PMID 38365771, 2024).
schizophrenia (1 paper, 2021). A major psychotic disorder characterized by abnormalities in the perception or expression of reality. "We noticed four of the DEGs (PLD2, PLCB3, PLAAT4, RPS27) involved in these pathways were also differentially expressed in the brain of patients with schizophrenia." (PMID 34630179, 2021).
Shwachman-Diamond syndrome (1 paper, 2018). "Gene expression profiles of bone marrow mononuclear cells from patients with Shwachman-Diamond syndrome revealed significant downregulation of RP genes, including RPS9, RPS20, RPL6, RPL15, RPL23, and RPL29, or upregulation of RPS27." (PMID 29954325, 2018).
cancer (20 papers, 2008 to 2026). A tumor composed of atypical neoplastic, often pleomorphic cells that invade other tissues. "Best predicted cancer immunotherapy proteins with BC were RPS27, SUPT4H1, CLPSL2, POLR2K and RPL38, and the most altered ones were POLR2K, ASH2L, MED30, NSL1 and RPRD2." (PMID 32444848, 2020). "Previous studies have shown that RPS27 is related to the activation of NF-κB pathways in cancer cells." (PMID 31921103, 2019). "The RPS27 protein is also known to be overexpressed in cancer cell lines which led to RPS27 being proposed as a putative biomarker for CaP." (PMID 29016636, 2017). "Abnormal high expression level of RPS27 is observed in several malignant tumors." (PMID 33968093, 2021). "Despite its significant overexpression in several malignant neoplasms, the expression of RPS27 in the central nervous system (CNS) is widely unknown." (PMID 32349320, 2020). "The best ranked cancer immunotherapy proteins related to BC were RPS27, SUPT4H1, and CLPSL2." (PMID 33537063, 2020). "However, current reports about the function of RPS27 are mostly on human cancers, and reports on other functions are few." (PMID 31921103, 2019). "Our analyses did not pick up RPL22, RPS27 (eS27), RPS15 and RPL10, although already described in cancer as well." (PMID 28147343, 2017).
tumor (18 papers, 2016 to 2025). "Nevertheless, the exact regulatory and signaling network controlling and involving RPS27 and its role in glioma stem-like cells, tumor-associated macrophages, and glioma tumor cells requires further clarification." (PMID 32349320, 2020). "Hematoxylin and eosin staining revealed a dramatic increase in the number of metastatic tumor nodules in the livers of mice inoculated with RPS27-OE-DU145 cells compared to those inoculated with EV-DU145 cells." (PMID 38365771, 2024). "RPS27 is released from the tumor by secretion or gradient diffusion and can, therefore, be measured in the patients’ serum." (PMID 32349320, 2020). "Almost all macrophages in tumor tissue were distinctly positive for RPS27, whereas only a minority of macrophages in inflammatory tissue was." (PMID 32349320, 2020). "RPS27, as a multifunctional protein, affects the translation of mRNA, and its aberrant expression may affect apoptosis and proliferation of tumour cells." (PMID 39098994, 2024). "Although RPS27 expression levels did not affect patient survival, their association with tumor cells and tumor-associated macrophages (TAMs) provides a rationale for future diagnostic and therapeutic interventions." (PMID 36425564, 2022). "Interestingly, CD68/RPS27 double staining indicated that almost all macrophages in tumor tissue were positive for RPS27 compared to a minority in inflammatory tissue." (PMID 36425564, 2022). "For this reason, we examined whether RPS27 expression correlates with tumor characteristics or patients’ clinical course." (PMID 32349320, 2020). "Although RPS27 expression levels did not affect the patients’ survival, their association with tumor cells and tumor-associated macrophages provides a rationale for a future investigation of a potential function during gliomagenesis and tumor immune response." (PMID 32349320, 2020). "Although RPS27 expression levels did not affect the patients’ survival, its association with tumor cells and tumor-associated macrophages provides a rationale for a future investigation of its potential function during gliomagenesis and tumor immune response." (PMID 32349320, 2020). "Due to this, the point of whether RPS27 could be used as a tumor-cell-specific IHC marker surfaced." (PMID 32349320, 2020). "In the C1 cluster (ribosomal small subunit assembly), genes such as RPS27 and RPL36 were significantly upregulated, indicating enhanced protein synthesis in tumor cells, which supports rapid proliferation." (PMID 40463392, 2025). "Several of these EPINs have promoters of differentially expressed genes (such as DLL1, STOM and SEC11C in the GEPIA tumor/normal dataset; ID2, RPS27, SEC11C, CASZ1, CRTC2, C5 and STOM in the LNCaP/LHSAR dataset; see Methods, Differential Gene Expression)." (PMID 38057321, 2023). "Therefore, whether these cells may indeed be tumor-associated macrophages came into question and double staining for RPS27 was thus performed in conjunction with the macrophage marker CD68 on the same slide, confirming the presence of RPS27-positive macrophages within the tumor." (PMID 32349320, 2020). "It revealed enhanced RPS27 expression in microvascular proliferation and pseudopalisading cells around necrosis, but not at the leading edge and by infiltrating tumor cells." (PMID 32349320, 2020). "Furthermore, RPS27 protein was specifically expressed in tumour cells and neurons but not in healthy astrocytes." (PMID 36569748, 2022). "RPS27 protein was specifically expressed in tumor cells and neurons, but not in healthy astrocytes." (PMID 32349320, 2020). "Although not suitable as a tumor cell-specific marker protein, our data may be a first hint for a potential role of RPS27 in tumor progression and immunological tumor response." (PMID 32349320, 2020).
tumor (continued). "Although tumor-associated macrophages represent up to 50% of the GBM cell mass, this staining did not exclude the possibility of another RPS27-positive, but GFAP- and CD68-negative cell type present within the tumor." (PMID 32349320, 2020).
infection (1 paper, 2025). The state of being infected such as from the introduction of a foreign agent such as serum, vaccine, antigenic substance or organism. "Previous studies comparing untreated HIV-infected individuals to healthy controls reported decreased expression of several ribosomal proteins, such as RPS27, RPL18A, RPL8, RPL26, RPL4, and RPS21, possibly reflecting impaired translational activity during active infection." (PMID 41226717, 2025).
RPS27 also shares sentences with these, for which no sentence is quoted: prostate carcinoma (3 papers); liver cancer (2); ovarian carcinoma (2); breast tumor (1); CNS tumors (1); colon adenocarcinoma (1); hepatocellular carcinoma (1); lung adenocarcinoma (1); lung carcinoma (1); lymphoma (1); pancreatic cancers (1); skin cancer (1); T-cell acute lymphoblastic leukemia (1).